GPI (glucose-6-phosphate isomerase)
Diseases named in the same sentence as GPI in open-access papers (continued):
Sharing a sentence is not in itself a finding about the gene and the disease.
tumor (continued). "GPI/AMF is secreted by tumour cells, protects cells from endoplasmic reticulum stress (ER stress) and apoptosis, and promotes cell motility, epithelial to mesenchyme transition and invasion and metastasis of tumour cells." (PMID 27103217, 2016). "Furthermore, vaccination of mice i.t. with TA-CIN alone, or TA-CIN/GPI-0100 via either i.t. or intramuscular injection significantly prolonged the survival of the tumor-bearing mice." (PMID 25560237, 2015). "In summary, our results suggest that isoscopoletin plays an anti-cancer role by regulating glycolysis-related proteins GPD2, GPI, Hsp90α and PGK2, and then inhibiting the glycolysis process and proliferation of tumor cells." (PMID 39509399, 2024). "Among them, GPD2, GPI, HSP90AA1 and PGK2 are involved in promoting glycolysis and tumor cell proliferation." (PMID 39509399, 2024). "The expression of differential genes related to PPP, including TKT, TKTL1, PGM1, GPI, FBP2, ALDOA and ALDOC, were all upregulated in WDLPS tumor samples, which were validated by Real-time Quantitative PCR (RT-qPCR)." (PMID 36557266, 2022). "To explore the correlation between the expression level of GPI and tumor immune response, we used the TIMER database to investigate immune infiltration in LUAD with different GPI expression levels." (PMID 34912709, 2021). "Target protein measurement of the tumor tissue revealed an increase in PGK2, GPD2, and GPI in response to the esculetin treatment." (PMID 32292350, 2020). "For each tumor, we dissected 4–5 separate frozen regions and determined the mRNA expression of TMPRSS2, GPI and ENO1 with qRT-PCR." (PMID 30478344, 2018). "We immunoprecipitated GAPDH in normal and 3MC induced tumor tissue lysates using antibody against GAPDH, and the precipitate was further probed with antibodies against PKM2, GPI, and GAPDH." (PMID 26911935, 2016). "Most of the upregulated genes (AMF, GPI, BSG, LGALS1, PAK2, PARVB, and VIM, among others) were involved in cell motility and adhesion, regulation of cell proliferation, tumor cell migration, metastasis, angiogenesis, and apoptosis." (PMID 24967369, 2014). "Given PE's involvement in the synthesis of GPI‐anchored proteins, the increased expression of PHOSPHO1 in tumor cells may reduce GPI‐anchored proteins on the cell membrane, thereby limiting the presence of some tumor antigens on the cell membrane." (PMID 40396905, 2025). "However, a positive correlation was identified in molecules that promote tumor progression like VEGFA, ALDOA, and GPI." (PMID 40806276, 2025). "This study suggests that isoscopoletin may exist an anti-tumor effect by regulating the glycolysis-related proteins GPD2, GPI, Hsp90α and PGK2, inhibiting the glycolysis process in HCC cells, then blocking the energy supply of tumor cells." (PMID 39509399, 2024). "Our qRT‐PCR experiments further revealed that METTL3 may promote the glycolysis capacity of ESCA cells by upregulating the expression of glycolysis‐related genes SLC2A1, GPI, PFKL, PGK1, ENO1 and PKM, thus facilitating tumour cell proliferation and migration." (PMID 38429907, 2024). "In vitro cell experiments have shown that interfering with DARS2 expression can inhibit the proliferation and migration of LUAD cells, promote cell apoptosis, and inhibit the glycolytic activity of tumor cells by inhibiting the expression of glycolytic related genes SLC2A1, GPI, ALDOA, and PGAM1." (PMID 37626419, 2023). "MET, GPI, ANGPTL4, HSPA5, TGFA, MIF, and ARTN were significantly up-regulated in tumor samples." (PMID 36447119, 2023). "Whether in Oncomine or in UALCAN, ADRB2, ARRB1, BDNF, etc., had a lower expression in tumor group than normal tissues, whereas CBLC, GPI, and PAK1 had a higher expression in tumor group than normal tissues." (PMID 35833114, 2022). "The rest genes, CD46, CXCL6, GPI, ITGB1, PLA2G6 and TNFSF4, were revealed for the negative association with tumor suppression." (PMID 35832540, 2022).
tumor (continued). "We observed that 4/7 FAS genes, GPAT4, CHP1, PCGF1, and GPI, show significant, negative hazard ratios (HR), consistent with a tumor suppressor signature, and that no other gene from our set shows a negative HR." (PMID 34764293, 2021). "Injection of TA-CIN alone, but not GPI-0100, into the tumor (i.t.)was similarly efficacious after cisplatin therapy, but the mice eventually succumbed." (PMID 25560237, 2015). "Similarly, the lncRNA NRCP has been shown to upregulate the expression of the glycolytic enzyme, glucose-6-phosphate isomerase (GPI), by promoting the interactions between STAT1 and RNA Pol II in the GPI gene promoter to promote its transcription and tumor progression." (PMID 39941838, 2025). "The KEGG signaling pathway enrichment results also indicated that isoscopoletin might play an anti-tumor role by affecting the core targets of glycolysis pathway, such as GPD2, GPI, Hsp90AA1 and PGK2, which were the intersection of most glycolysis-related pathways." (PMID 39509399, 2024). "In line with this, the lactate levels increased both in tumor and peritumoral tissues, as well as the expression of glutamine transporters (i.e., SLC1A5) and glycolytic enzymes, such as glucose-6-phosphate isomerase (GPI), phosphoglycerate kinase (PGK1), aldolase A (ALDOA) and hexokinase 2 (HK2)." (PMID 33924061, 2021). "Since a strong TA-CIN-specific CD4+ T cell response was observed after vaccination of naïve BALB/c mice with TA-CIN/GPI-0100, we examined whether this TA-CIN-specific CD4+ T cell response was also induced in TC-1 tumor-bearing C57BL/6 mice after vaccination using both fresh and frozen vaccine." (PMID 25560237, 2015).
cancer (61 papers, 1978 to 2025). A tumor composed of atypical neoplastic, often pleomorphic cells that invade other tissues. "GPI knock-out (KO) has been shown to inhibit cancer cell growth, suggesting a significant role for GPI in cancer progression." (PMID 38419074, 2024). "For malignant cells, consistently upregulated metabolic genes were predominantly associated with cancer hallmark pathways, including glycolysis (GAPDH, GPI and LDHA), OXPHOS (COX6B1 and ATP5MC2), and nucleotide metabolism (TK1, GUK1, NME1)." (PMID 39393173, 2024). "There in vivo and in vitro studies showed that RP11-620J15.3 play role in cancer proliferation and metastasis by enhancing the Warburg effect through glucose-6-phosphate isomerase in HCC cells." (PMID 38336706, 2024). "In recent years, it has been reported that there was an aberrant expression of GPI in several cancers." (PMID 36246907, 2022). "For example, NT5E and TNAP are GPI-anchored proteins that can be released by endogenous phospholipase C cleavage of GPI, via microvesicles or via exosomes from cancer cells." (PMID 35784885, 2022). "In this study, we first tried to determine the expression and prognostic value of the GPI gene in cancer and found that GPI expression was upregulated in LUAD." (PMID 34912709, 2021). "Cripto-1, which is a GPI-anchored membrane-bound protein that functions as a co-receptor of Nodal, is a marker of cancer stem cells." (PMID 34065315, 2021). "When esculetin exhibits an anti-cancer effect, GPI, GPD2, and PGK2 with a higher degree were selected for the following experiments." (PMID 32292350, 2020). "GAPDH interacts with an alternatively spliced isoforms of pyruvate kinase, PKM2 and GPI in cancer cells." (PMID 26911935, 2016). "Expression of genes within the glycolytic pathway (GAPDH, TPI1 and GPI) remained highly correlated in both in NSCLCs and non-cancer control tissue samples." (PMID 23620736, 2013). "In this context, deactivation of transketolase and glucose-6-phosphate isomerase may be considered as potential drug targets to resist cell growth, fermentation and proliferation as well as energy supply in human cancer cells." (PMID 33510857, 2021). "GPIT and GPI have been described as promoting cancer growth." (PMID 34659659, 2021). "To further verify the expression level of GPI in LUAD, we selected another four independent external GEO datasets (validation cohort) to analyze the GPI transcription levels of cancer tissues and adjacent tissues in LUAD, including GSE10072, GSE32863, GSE7503, and GSE30219." (PMID 34912709, 2021). "Among six drug targets under consideration, deactivation of transketolase and glucose-6-phosphate isomerase may be the most potential to slow down cancer progression by reducing cell proliferation, growth, fermentation and energy supply." (PMID 33510857, 2021). "GPI transamidase (GPIT) and GPI anchored proteins are key markers of different types of cancers." (PMID 34659659, 2021). "Inhibition of GPI expression by siRNA reduces hypoxia induced cancer cell motility." (PMID 26911935, 2016). "The expression of glycolytic enzymes, e.g., glucose-6-phosphate isomerase (GPI), GLUT1 and MCT1, also increases with the different ccRCC stages and represents the independent prognostics marker for this cancer type." (PMID 36902344, 2023). "The most significantly differentially co-expressed link is glucose-6-phosphate isomerase (GPI), a known biomarker of cancer that is involved in glycolysis." (PMID 37172717, 2023). "We further investigated the effects of the interplay and the underlying mechanisms between circ‐CTNNB1 and RBM15 on the regulation of target genes (GPI, HK2 and PGK1) and cancer progression in OS cells." (PMID 36181462, 2023). "The expression of SLC6A8 exhibited the strongest positive correlation with that of ADM, GPI, NDRG1, PGK1, and PNCK, and their correlation with SLC6A8 expression in distinct cancer types were illustrated by the heatmap, respectively." (PMID 36061183, 2022).
cancer (continued). "Along these lines, lactate production and secretion was enhanced, which corresponds to Warburg’s initial observation, and was abolished by the disruption of glucose-6-phosphate isomerase (GPI) in LS174T and B16 cancer cell lines." (PMID 31083487, 2019). "This innovation was applied to the exploration of IgG repertoires from mice immunized with various antigens, including the vaccine target Tetanus Toxoid (TT), the multifunctional enzyme Neuroleukin/Glucose-6-Phosphate Isomerase (GPI), and the membrane-bound cancer target Tetraspanin-8 (TSPAN8)." (PMID 40710059, 2025). "Knocking out glucose-6-phosphate isomerase (GPI), the enzyme that catalyzes the conversion of glucose-6-phosphate (G6P) to fructose-6-phosphate (F6P), upregulated OXPHOS and sustained the survival of cancer cells." (PMID 36768924, 2023). "The mRNA levels of three out of six genes we tested (SLC2A3, GPI, and PDK3) were selectively decreased by PRDX2 and PRDX4 during prolonged hypoxia, suggesting that PRDX2 and PRDX4 may be negative regulators of glucose reprogramming in cancer cells exposed to prolonged hypoxia." (PMID 26837221, 2016).
infection (21 papers, 2005 to 2025). The state of being infected such as from the introduction of a foreign agent such as serum, vaccine, antigenic substance or organism. "Upon UK1-TuMV infection, GPi/GPm depended on the allometric group (Wald χ21,166 = 17.95, P < 1 × 10−4), this ratio being smaller for Group 1 than for Group 2 plants." (PMID 32211198, 2020). "Thus TA-CIN/GPI-0100 vaccination might protect against future infection (with a different type or HPV16 after its clearance) or potentially limit spread of infection within the host." (PMID 25560237, 2015). "infection was analyzed by sequencing gene fragments (GPX, GPI, HMCOAR, LAP, PDH and COII) or by mini-exon multiplex PCR." (PMID 36038947, 2022). "In contrast, transcriptional levels of beta-glucosidase 24-like isoform, glucose-6-phosphate isomerase, and the central circadian clock proteins CCA1 were notably induced by the infection of E. gansuensis at 0 mM NaCl concentration." (PMID 36294657, 2022). "Post-infection upregulated 20 transcripts in B-48, including G6PD (6 DEGs), GSDH (3 DEGs), GDPGP1 (4 DEGs), GPI (1 DEG), UGDH (1 DEG), UGPUT (3 DEGs), UGGT (1 DEG) and GPT2 (1 DEG)." (PMID 34948367, 2021). "In addition, many metabolic enzymes such as glucose-6-phosphate isomerase and phosphoglycerate kinase 1 are also modified by ISG15 following infection with Listeria either at dimerization domains or at active sites of the enzyme." (PMID 31772204, 2019). "This was attributed to the fact that the binding of autoimmune APLA to phospholipid is enhanced by the cofactor β2 GPI (i.e. β2 GPI dependent) while the binding of infection induced APLA is not enhanced by this cofactor (i.e. β2 GPI independent)." (PMID 16176580, 2005). "THP-1 cells were, therefore, stimulated with 1 μg/ml LPS, a concentration mimicking an infection from Gram-negative bacteria, in the presence or absence of 100 μg/ml bLf, and production of IL-6 and IL-1β as well as expression of Fpn, TfR1, Ftn, and Cp-GPI was assessed." (PMID 28663751, 2017).
gastrointestinal neoplasms (2 papers, 1983 to 2024). "GI tumor tissues with higher CBX3 K10la intensities exhibited elevated protein levels of hexokinase 2 (HK2), glucose‐6‐phosphate isomerase (GPI), and pyruvate kinase M (PKM)." (PMID 39018247, 2024).
autosomal recessive hereditary disease (1 paper, 2022). "Glucose-6-phosphate isomerase (GPI) deficiency (MIM 613470), one of hereditary nonspherocytic hemolytic anemias (HNSHA), is a rare autosomal recessive hereditary disease caused by homozygous or compound heterozygous mutations of GPI gene on chromosome 19q13." (PMID 35915427, 2022).
movement disorder (1 paper, 2021). Neurological conditions resulting in abnormal voluntary or involuntary movement, which may impact the speed, fluency, quality and ease of movement. "Although, international experience with GPi DBS in DDS demonstrated a very significant efficacy on the hyperkinetic component of movement disorder, it has been shown that a prominent hypertonic dystonia is not corrected by the neuromodulation of GPi." (PMID 34070634, 2021).
neurological disease (1 paper, 2016). "In fact, STN and GPi protein lists respectively revealed 412 and 381 different species associated to neurological disease pathways, which represented 38.1 and 42.6 % of the total identified proteins in STN and GPi, respectively." (PMID 26822202, 2016).
GPI also shares sentences with these, for which no sentence is quoted: Parkinsonism (8 papers); antiphospholipid syndrome (6); experimental autoimmune encephalomyelitis (4); hepatocellular carcinoma (4); Autoimmunity (3); myeloid leukemia (3); Sepsis (3); glioblastoma (2); hemoglobinopathies (2); metastatic disease (2); segmental dystonia (2); acute pancreatitis (1); allergies (1); Alzheimer disease (1); angiosarcoma (1); Arterial thrombosis (1); atherosclerosis (1); atrial septal aneurysm (1); autoimmune myocarditis (1); autoimmune uveitis (1); bladder cancer (1); bone marrow failure (1); cardiovascular diseases (1); cervical cancer (1); cervical dystonia (1); cholangiocarcinoma (1); coagulopathies (1); cognitive decline (1); congenital dyserythropoietic anemia (1); cyst (1).
A further 49 diseases each share a sentence with GPI in 1 paper.